CREBBP (CREB binding lysine acetyltransferase )
Diseases named in the same sentence as CREBBP in open-access papers (continued):
Sharing a sentence is not in itself a finding about the gene and the disease.
breast cancer (continued). "In another series, 4 of 5 female patients with MYST3/CREBBP related AML had received adjuvant chemotherapy with adriamycin based regimens for breast cancer." (PMID 25548695, 2014). "We found that lysine at multiple locations of NUCB2 may be acetylated, and the acetyltransferases involved are mainly CREBBP, which has been reported to be activated in breast cancer and to elevate acetylation of many substrates." (PMID 37277807, 2023). "Taken together, modulation of PPARγ signaling and CREBBP depends on the breast cancer subtype." (PMID 36114448, 2022). "However, dependence on the acetyltransferase activity of CREBBP/EP300 in ER+ breast cancer is consistent with the known physical and functional links between CREBBP/EP300 and ER and has been corroborated in another recently published study." (PMID 35353838, 2022). "To explore the transcriptional events underlying the phenotypic response to CREBBP/EP300 acetyltransferase inhibition, we carried out RNA sequencing analysis of three breast cancer cell lines (MCF7, T47D, and ZR751) treated with CPI-1612 alone or in combination with Fulvestrant." (PMID 35353838, 2022). "Further studies on RGZ activity targeting CREBBP in breast cancer angiogenesis are required." (PMID 36114448, 2022). "Thus, while CREBBP/EP300 HAT inhibition globally reduces H3K27 acetylation in ER+ breast cancer cells, changes in chromatin accessibility are much more circumscribed." (PMID 35353838, 2022). "Similarly, CREBBP is highly expressed in breast cancer patients, and CREBBP is involved in the regulation of cellular events in advanced prostate cancer." (PMID 34149798, 2021). "However, a literature has pointed out that the gene CREBBP is also involved in the same function as Breast Cancer and Reported Genes by studying the function and pathway of the new gene." (PMID 31888623, 2019). "Mutations in CREBBP and SMAD4 have only been occasionally reported in breast cancer." (PMID 27270325, 2016). "In the PPI network of 308 genes, several hub genes (ESR1, BRCA1, CREBBP, ERBB2, and LCK) are known to play critical roles in breast cancer development." (PMID 39888956, 2025). "In this study we show that CREBBP/EP300 HAT inhibition with the potent and selective inhibitor CPI-1612 can inhibit the growth of breast cancer cell lines in vitro and impede tumorigenesis in vivo at well tolerated doses with demonstrated target engagement." (PMID 35353838, 2022). "Using the potent and selective inhibitor CPI-1612, we show that CREBBP/EP300 acetyltransferase inhibition potently suppresses in vitro and in vivo growth of breast cancer cell line models and acts in a manner orthogonal to directly targeting ER." (PMID 35353838, 2022). "Given the known functional link between CREBBP/EP300 and ER signaling, we further explored the impact of CPI-1612 in the context of ER+ breast cancer." (PMID 35353838, 2022). "Further, we use this potent and selective inhibitor to provide insight into the role of CREBBP/EP300 in defining the transcriptional programs and chromatin landscape of ER+ breast cancer." (PMID 35353838, 2022). "This study explored the potential targets of RGZ as antiangiogenic agents in breast cancer therapy and highlighted FABP4, ADIPOQ, PPARG, PPARGC1A, CD36, and CREBBP as potential targets of RGZ." (PMID 36114448, 2022). "For example, by interacting with CREBBP to promote the transcription of H3K27Ac and CREB1, LINC01857 promote the progression of breast cancer." (PMID 34425868, 2021). "In primary breast cancers, circRNAs of CREBBP, CNOT2, and RERE and RNAi-mediated knockdown of circRNA circCNOT2 was shown to significantly reduce the viability of two breast cancer cell lines: MCF-7 and BT-474." (PMID 32467674, 2020).
breast cancer (continued). "CREBBP, NUMA and SPEN have not been linked to breast cancer by the COSMIC CGC but have been statistically determined to be breast cancer drivers by IntOGen." (PMID 39010058, 2024). "Notably, A485 exposure has also demonstrated the ability to downregulate estrogen receptor protein levels in breast cancer, and EP300/CREBBP acetyltransferase inhibition curtails estrogen signaling through FOXA1-bound enhancers." (PMID 38564048, 2024). "Given the functional link between CREBBP/EP300 and ER, we investigated whether inhibition of CREBBP/EP300 acetyltransferase activity would impact the viability of ER+ breast cancer cell lines." (PMID 35353838, 2022). "The mRNA expression levels of FABP4, ADIPOQ, PPARG, CD36, and PPARGC1A were significantly lower in patients with breast cancer, whereas the mRNA levels of CREBBP were not different between patients with breast cancer and normal breast tissues." (PMID 36114448, 2022). "Conclusions were that CHD4 coactivates HIF to promote breast tumor growth, and that different mRNAs were also up-regulated in human breast tumors (ZMYND8, KDM4C (JMJD2C), CDK8, CREBBP (CBP), KAT), suggesting the heterogeneity of epigenetic regulation of HIF in breast cancer." (PMID 33981601, 2021). "The MYST3/CREBBP AML tends to develop within 2 years of adjuvant chemotherapy, especially for breast cancer, without preceding myelodysplasia." (PMID 25548695, 2014). "We further demonstrate that CREBBP/EP300 HAT inhibition acts in an overlapping but nonidentical manner to the standard of care Fulvestrant, supporting its potential development in combination or resistance settings in ER+ breast cancer." (PMID 35353838, 2022).
B-cell lymphomas (30 papers, 2015 to 2025). "Loss-of-function mutations in the epigenetic modifier CREBBP are common oncogenic drivers in B-cell lymphomas, particularly in the GCB subtype." (PMID 40243506, 2025). "Examination of alterations in key pathways implicated in B-cell lymphomas suggests involvement in chromatin remodelling (CREBBP and EP300) and regulators of NF-κB signalling (TNFAIP3, BCL10, MYD88, CD79B and CARD11) were affected." (PMID 39460552, 2024). "Based on a strong rationale that B-cell lymphomas with CREBBP mutations are dependent on HDAC3 activity, HDAC3 inhibition has been recently demonstrated as a promising strategy for those mutant cases while wild-type tumors show modest responses." (PMID 39117798, 2024). "CREBBP/EP300 mutations as a major pathogenetic mechanism shared by common forms of B-cell non-Hodgkin lymphoma (B-NHL) have direct implications for the use of drugs targeting the acetylation/deacetylation mechanism." (PMID 36831561, 2023). "FL is a common type of B cell lymphoma and can be classified into two subtypes by the presence of CREBBP mutation." (PMID 35706040, 2022). "For example, recent studies demonstrated that somatic inactivating mutations of the histone-acetyltransferase (HAT) domain of CREBBP/EP300 impair its acetyltransferase activity in certain types of non-Hodgkin B-cell lymphoma and bladder cancer." (PMID 32493417, 2020). "CREBBP, which is also mutated in other types of B cell lymphomas, is an epigenetic regulator, belonging to the KAT3 family of histone/protein lysine acetyltransferases." (PMID 32316399, 2020). "As the second most frequently mutated chromatin modifying gene in B-cell lymphoma, the CREBBP gene is recurrently mutated in 65% of FL patients and 16% of DLBCL." (PMID 31788471, 2019). "Furthermore, loss-of-function mutations in CREBBP lead to increased development of B-cell lymphomas in murine models." (PMID 38473705, 2024). "CREBBP deficiency promotes the development of B-cell lymphoma." (PMID 36831561, 2023). "Our results thus suggest that targeting the remaining HAT function may hold therapeutic potential for B-cell lymphomas with deficiency in either CREBBP or EP300." (PMID 33911074, 2021). "Other models of CREBBP-mutated B-ALL and B-cell lymphoma have implicated changes in cell cycle, metabolism, DNA damage response and apoptosis." (PMID 40393984, 2025). "Mutations in the glucocorticoid receptor regulatory network pathway, including CREBBP, tended to occur early, while mutations in the TNF pathways tended to happen late in B-cell non-Hodgkin lymphoma." (PMID 39868264, 2025). "In CREBBP-mutant B-cell lymphoma cells, HDAC3 inhibition shows strong anti-tumor effects via H3K27ac restoration." (PMID 39117798, 2024). "The reported co-occurring pattern of CREBBP and KMT2D mutations across B-cell lymphomas prompted us to further validate those findings in publicly available patient datasets." (PMID 38570506, 2024). "While UTX mutations are rare in GC B-cell lymphomas, a high incidence of inactivating mutations in the components of COMPASS and its partner HATs, including KMT2D, CREBBP, and EP300, has been reported." (PMID 37198323, 2023). "CREBBP and EP300 mutations are one of the main pathogenic mechanisms of B cell non-Hodgkin lymphoma (B-NHL) and have a direct impact on the use of drugs targeting acetylation/deacetylation mechanisms." (PMID 37884941, 2023). "The synthetic lethal interaction between CREBBP and EP300 genes, two frequently mutated epigenetic modulators in B-cell lymphoma, was further validated in the previously published CRISPR-Cas9 screens and inhibitor assays." (PMID 33911074, 2021).
B-cell lymphomas (continued). "Two interacting HAT genes, CREBBP and EP300, are recurrently mutated in B-cell lymphoma and are most prevalent in subtypes that align with the GCB-cell stage of differentiation." (PMID 26473533, 2015). "Interestingly, CREBBP, a key gene in this pathway, is a known driver gene of B-cell non-Hodgkin lymphoma." (PMID 39868264, 2025). "Furthermore, we identify frequent pathogenic variants involving CREBBP and EP300, both of them associated with epigenetic abnormalities in GC-derived B-cell lymphomas such as cHL." (PMID 38473705, 2024). "We concluded that similarly to CIITA, EZH2, and CREBBP mutations, IRF8 variants may add to the pathogenesis of B cell lymphomas by impairing antigen presentation in the context of MHCII." (PMID 38996030, 2024). "CREBBP and KMT2D mutations frequently co-occur in B cell lymphomas with unclear significance." (PMID 38570506, 2024). "Herein, we explored the puzzling co-occurrence of somatic mutations in the two enhancer activating chromatin modifier proteins CREBBP and KMT2D in B-cell lymphomas." (PMID 38570506, 2024). "In consistence with experimental data showing that HDACIs can rescue deficits in histone acetylation induced by CREBBP/EP300 mutations in B-cell lymphoma, our results provided clinical evidence that tucidinostat may mitigate the negative prognostic impact of CREBBP/EP300 mutations on DLBCL." (PMID 33097085, 2020).
leukemia (28 papers, 2006 to 2025). A malignant (clonal) hematologic disorder, involving hematopoietic stem cells and characterized by the presence of primitive or atypical myeloid or lymphoid cells in the bone marrow and the blood. "The remaining unremitted children included one with DEK::NUP214, one with secondary leukemia associated with KAT6A::CREBBP, and another with AXSL1 and SRSF2." (PMID 41264489, 2025). "CREBBP is expressed in leukemia cells and normal B-cell progenitors, and the mutant CREBBP alleles are expressed in ALL cell lines harboring mutations." (PMID 26543507, 2015). "We then analyzed the selective dependency on EP300 and CREBBP of a series of leukemia compared to other tumor cells in DepMap database, highlighting EP300/CREBBP potential targeting in AML cells." (PMID 38693103, 2024). "Our observations found that EP300/CREBBP selectively inhibitor A-485 exerted a robust eradicating leukemia effect in MLL-r AML cells." (PMID 38693103, 2024). "Targeting EP300/CREBBP holds great promise for treating leukemia with some certain cytogenetic abnormalities." (PMID 38693103, 2024). "EP300/CREBBP inhibitor selectively exerted potent anti-leukemia activity through blocking the MLL-r-BET complex binding to H3K27Ac modification on critical genes loci, distinct from global histone acetylation." (PMID 38693103, 2024). "Collectively, our study identified EP300/CREBBP as a critical epigenetic driver of MLL-r leukemia and validated their therapeutic potential through targeting inhibition, offering a promising avenue for improving clinical outcomes in this aggressive leukemia." (PMID 38693103, 2024). "Our research underscored the synergistic effect of EP300 and CREBBP in regulating MLL-r leukemia cell proliferation." (PMID 38693103, 2024). "HMGN1 overexpression increases chromatin accessibility, expression, and H3K27ac at loci important for HSCs and leukemia, including many CREBBP/EP300 targets." (PMID 36831561, 2023). "Recurrent ITDs lacking DNA support are also present; one such example is an ITD of CREBBP exon 2, detected in three leukemia samples (i.e., SJETV092_D, SJPHALL005_D, SJPML030005_D1) in our benchmark data set." (PMID 32466770, 2020). "Inhibitors of CREBBP/EP300 bromodomains show promising pre-clinical activity in models of leukemia characterized by the presence of translocations leading to the presence of fusion proteins containing such bromodomains." (PMID 28054944, 2017). "Importantly, this effect was specific to MLL-r cells, exhibiting minimal impact on MLL wild-type AML cell and normal hematopoiesis, and highlighting the potential of EP300/CREBBP as selective therapeutic targets for this aggressive leukemia subtype of MLL-r." (PMID 38693103, 2024). "Importantly, targeting the bromodomain of EP300/CREBBP has shown promising efficacy in several malignancies driven by transcriptional activator-driven malignancies, including leukemia, lymphoma and myeloma." (PMID 38693103, 2024). "We found that the proliferation and colony formation functions of MLL-r AML cells were suppressed significantly upon loss of EP300 or CREBBP, while, the proliferation of the MLL wild-type cells was less influenced, highlighting a specific vulnerability of MLL-r leukemia to EP300/CREBBP depletion." (PMID 38693103, 2024). "Pathogenic variants in CREBBP cause Rubinstein–Taybi syndrome (RTS), a rare genetic disease characterized by short stature, mental retardation, and increased risk of developing solid malignancies and leukemia." (PMID 37569667, 2023). "Genetic abnormalities of CREBBP/EP300 are also common in leukemia." (PMID 36831561, 2023). "Similarly, inhibition of CREBBP/EP300 BRDs specifically affected differentiation of leukemia-initiating cells after prolonged exposure." (PMID 27757418, 2016). "However, the precise role of EP300/CREBBP in MLL-r leukemia remains largely unexplored." (PMID 38693103, 2024).
leukemia (continued). "Moreover, we provided a proof of concept that targeting EP300/CREBBP is a potential therapeutic for MLL-r AML, as validated by in vitro and in vivo leukemia models." (PMID 38693103, 2024). "Simultaneous targeting of EP300/CREBBP and BET had synergistic anti-leukemia effects in MLL-r AML." (PMID 38693103, 2024). "Among other common events in this type of cancer are mutations in genes that encode enzymes modifying histones, such as the histone acetyltransferases CREBBP (CREB Binding Protein) and EP300 (E1A Binding Protein P300), as well as the histone methyltransferases MLL (Mixed Lineage Leukemia)." (PMID 38203275, 2023). "Importantly, CREBBP and EP300 are also found as oncogenic fusion partners of the histone acetyltransferase gene MOZ or MLL in leukemia." (PMID 31552175, 2019). "These efforts and additional validation experiments revealed PSIP1, CREBBP, and kinase FLT3 representing known vulnerabilities in KMT2A-r, as well as ARID4B, MBD3, and BMPR2 as potential candidates to be considered as novel therapeutic targets in this aggressive type of leukemia." (PMID 37686014, 2023).
diffuse large B-cell lymphoma (26 papers, 2014 to 2025). "It is notable that the EP300/CREBBP pathway mutational signatures uncovered in this study are also seen in diffuse large B-cell lymphoma, where they are associated with NOTCH activation via negative regulation of FBXW738." (PMID 41162424, 2025). "CREBBP gene encodes chromatin-modifying enzymes and has been described in diffuse large B cell lymphoma, acute lymphoblastic leukemia, and lung cancer." (PMID 38435839, 2024). "CREBBP encodes chromatin-modifying enzymes such as the histone acetyl-transferases and has been studied in diffuse large B cell lymphoma, acute lymphoblastic leukaemia, and lung cancer." (PMID 31974418, 2020). "Mutations of CREBBP are frequently found in acute lymphoblastic leukemia or diffuse large B‐cell lymphoma, and mutant‐ROBO2 is detected in patient of MDS." (PMID 29769258, 2018). "Interestingly, these genes and enhancers are also repressed in CREB binding protein (CREBBP)‐mutated diffuse large B‐cell lymphomas." (PMID 40599235, 2025). "Besides, CREBBP mutations have also been reported to play a role in the initiation and progression of acute lymphoblastic leukemia and diffuse large B-cell lymphoma." (PMID 36599976, 2023). "Moreover, authors checked whether the CREBBP mutations occurred at stem and progenitor level in 1 patient with diffuse large B-cell lymphoma (DLBCL) and 2 patients with follicular lymphoma (FL), without BM infiltration." (PMID 38440231, 2024). "In diffuse large B-cell lymphoma (DLBCL), CREBBP/EP300 mutations have been found to primarily affect the HAT-lysine acetyltransferase 11 (KAT11) domain." (PMID 36831561, 2023). "In the present study, we aim to examine the relationship between genetic polymorphism and transcriptional expression of cyclic AMP response element binding protein (CREBBP) and the risk of diffuse large B-cell lymphoma (DLBCL)." (PMID 31366566, 2019). "Consistent with our analysis, it was reported that CREBBP can alter tumor-associated macrophage polarization via the FBXW7-NOTCH-CCL2/CSF1 axis, resulting in tumor progression in diffuse large B-cell lymphoma." (PMID 39868264, 2025). "In a Phase 2 study examining the efficacy of mocetinostat, an oral HDACi, researchers investigated its effects on patients with relapsed or refractory diffuse large B-cell lymphoma (DLBCL) or follicular lymphoma (FL) who have mutations in the CREBBP/EP300 genes." (PMID 40426926, 2025). "In a cellular model of diffuse large B-cell lymphoma (DLBCL), the inhibition of HDAC3 rescues the aberrant epigenetic programming associated with CREBBP mutations, enhancing BCL6-mediated antigen presentation and the release of IFN-γ." (PMID 40006729, 2025). "As previously reported for diffuse large B-cell lymphoma (DLBCL) and follicular lymphoma (FL), pathogenic variants involving the CREBBP and EP300 genes seem to arise particularly frequently in patients with cHL showing chemorefractory disease." (PMID 38473705, 2024). "The genetic test results of the left frontal parietal lobe lesion result revealed 23 gene mutations, including MYD88, CD79B, CDKN2A, PIM1, RELN, PCLO, CREBBP, and so on, supporting the diagnosis of diffuse large B-cell lymphoma." (PMID 36599976, 2023). "In various B cell lymphomas, such as diffuse large B cell lymphoma (DLBCL) or follicular lymphoma (FL), somatic mutations in KMT2D (MLL2), EZH2, CREBBP, and TET2 are frequent events, affecting germinal center (GC) formation and affinity maturation." (PMID 37648814, 2023). "The result showed 23 gene mutations, including MYD88, CD79B, CDKN2A, PIM1, RELN, PCLO, CREBBP, and so on, supporting the diagnosis of diffuse large B-cell lymphoma." (PMID 36599976, 2023). "NOTCH signaling mediates M2 polarization of TAMs in diffuse large B cell lymphoma (DLBCL) through the CREBBP/EP300-FBXW7-NOTCH-CCL2/CSF1 pathway." (PMID 35332121, 2022).